RHPN1-AS1 (RHPN1 antisense RNA 1)
Synonyms: C8orf51; MGC3113
Gene: Long non-coding RNA gene on chromosome 8 (143,366,422 to 143,368,637, reverse strand). Ensembl gene ENSG00000254389.
Diseases named in the same sentence as RHPN1-AS1 in open-access papers:
RHPN1-AS1 is named in the same sentence as 2 diseases in open-access papers, as found by Europe PMC text mining. Sharing a sentence is not in itself a finding about the gene and the disease. The quoted sentences say what the papers report.
uveal melanoma (2 papers, 2017 to 2021). A melanoma derived from melanocytes of the uveal tract. "RHPN1 antisense RNA 1 (RHPN1-AS1) knockdown significantly inhibited uveal melanoma (UM) cell proliferation and migration in vitro and in vivo." (PMID 29383105, 2017). "The long non-coding RNA RHPN1 antisense RNA 1 (RHPN1-AS1) was found to promote the progression of several tumors, including uveal melanoma, cervical cancer, and HCC." (PMID 33869043, 2021).
RHPN1-AS1 also shares sentences with these, for which no sentence is quoted: cervical cancer (1 paper).